IL7 (interleukin 7)
Description:
Hematopoietic cytokine that plays an essential role in the development, expansion, and survival of naive and memory T-cells and B-cells thereby regulating the number of mature lymphocytes and maintaining lymphoid homeostasis. Mechanistically, exerts its biological effects through a receptor composed of IL7RA subunit and the cytokine receptor common subunit gamma/CSF2RG. Binding to the receptor leads to activation of various kinases including JAK1 or JAK3 depending on the cell type and subsequently propagation of signals through activation of several downstream signaling pathways including the PI3K/Akt/mTOR or the JAK-STAT5.
Synonyms: IL-7; IMD130
Tractability: Antibody: UniProt places it where antibodies can reach, with high confidence; its Gene Ontology location is reachable by antibodies, with high confidence; UniProt predicts a signal peptide or a membrane-spanning region.
Safety:
Unwanted effects reported when the protein is acted on. In parentheses: how it was acted on, where the effect was seen, and who reports it.
adverse events (source: ClinPGx)
Gene: Protein-coding gene on chromosome 8 (78,675,743 to 78,805,523, reverse strand). Ensembl gene ENSG00000104432.
Subcellular location: Secreted
Pathways (Reactome):
Immune System: Interleukin-7 signaling
Gene Ontology:
Molecular function: cytokine activity; protein binding; growth factor activity; interleukin-7 receptor binding; cytokine receptor binding
Biological process: cytokine-mediated signaling pathway; interleukin-7-mediated signaling pathway; positive regulation of chemokine production; positive regulation of cytokine-mediated signaling pathway; animal organ morphogenesis; bone resorption; cell-cell signaling; humoral immune response; negative regulation of apoptotic process; positive regulation of B cell proliferation; positive regulation of cell population proliferation; positive regulation of T cell differentiation; immune response
Cellular component: extracellular matrix; extracellular region
Genetic constraint (gnomAD): Loss-of-function variants: 0 observed, 1.59 expected, observed/expected ratio (o/e) 0, 90% interval 0 to 1.52. That is too few expected variants to judge how well the gene tolerates losing a copy. Missense variants: 10 observed, 16.62 expected, observed/expected ratio (o/e) 0.6, 90% interval 0.37 to 1.02. Synonymous variants: 4 observed, 5.63 expected, observed/expected ratio (o/e) 0.71, 90% interval 0.35 to 1.56.
Homologues: Orthologues: chimpanzee IL7 (99% identical), macaque IL7 (96% identical), pig IL7 (73% identical), rabbit IL7 (68% identical), dog IL7 (62% identical), mouse Il7 (60% identical), rat Il7 (60% identical), guinea pig IL7 (57% identical).
Diseases named in the same sentence as IL7 in open-access papers:
IL7 is named in the same sentence as 477 diseases in open-access papers, as found by Europe PMC text mining. Sharing a sentence is not in itself a finding about the gene and the disease. The quoted sentences say what the papers report.
COVID-19 (330 papers, 2020 to 2025). A disease caused by infection with severe acute respiratory syndrome coronavirus 2. "COVID-19 severity is linked to elevated levels of inflammatory mediators, including cytokines (e.g., IL-2, IL-7, IL-10, IFN-γ, and TNF-α) and chemokines (e.g., G-CSF, MCP1, MIP1α, and CXCL10), as well as markers like C-reactive protein, ferritin, and D-dimers." (PMID 40649865, 2025). "We and others have previously shown profound perturbation of T cell homeostasis during acute COVID-19, including marked T cell lymphopenia, which was associated with increased serum IL-7 concentrations." (PMID 41310351, 2025). "We identified IL-7, IL-15, and lymphotoxin-α as central mediators underlying severe COVID-19, related respiratory failure, and high-risk immune signatures." (PMID 38368384, 2024). "Although the role of IL-7 in ALI is unclear, elevated IL-7 has been associated with the most-severe cases of ARDS in COVID-19-infected patients." (PMID 37373199, 2023). "Orumaa and co-authors revealed that severity of COVID-19 is linked to cytokine storm, which occurs when levels of inflammatory mediators such as IL-7, IL-10, and MIP are up-regulated." (PMID 37053191, 2023). "IL-8 is a chemokine associated with lymphopenia in severe cases of COVID-19, and IL-7 is a cytokine involved in the maintenance of T cells and is associated with lymphocyte counts." (PMID 37460909, 2023). "Levels of Eotaxin-3, MIP-1α, IL-12p70, TNF-α, IL-7, GM-CSF, and IL-23p40 were also significantly associated with monocyte-derived cfDNA in SOTRs with COVID-19 (p<0.05 and FDR<0.25)." (PMID 35075453, 2022). "In COVID-19, circulating IL-7 was found to be elevated with levels that associate with disease severity." (PMID 36287942, 2022). "It is currently acknowledged that severe forms of COVID-19 are associated with the release of cytokines, such as IL-2, IL-6, IL-7, IL-10, tumor necrosis factor (TNF), and granulocyte colony-stimulating factor (GCSF)." (PMID 35743583, 2022). "Elevated IL-7 levels were found to be associated with the severity of COVID-19 and admission to intensive care units." (PMID 36012146, 2022). "IL-7 is associated with lymphocytes returning to a reference level, appearing to reverse a pathologic hallmark of COVID-19." (PMID 36286038, 2022). "In a recent study with a small number of patients with COVID-19, it was shown that IL-7 can be safely administered and it was associated with an increase in lymphocytes count, appearing to counteract a pathologic hallmark of COVID-19." (PMID 36558048, 2022). "IL-7 promotes lymphocytic count increase counteracting the lymphocytopenia, a pathologic hallmark of severe COVID-19." (PMID 36558048, 2022). "Some studies have also shown that cytokine storms, such as elevated levels of interleukin-6, interleukin-7, and granulocyte-macrophage cloning replicator, are associated with more severe forms of COVID-19 in people with hypertension." (PMID 34676114, 2021). "While cytokine storm underlies the severe symptoms of COVID-19, interleukin 7 (IL-7) and IL-2 increase in plasma of COVID-19 patients, and IL-7 and IL-2 reduce the expression of ACE2 in mice." (PMID 33799583, 2021). "In one of the very first reports of the clinical course of COVID-19 patients, as early as March 2020, serum increase in interleukin (IL)-2, IL-7, GMCSF, IP-10, MCP 1, MIP1-α, and TNF-α was associated to disease severity." (PMID 33019628, 2020). "In COVID-19 patients, a profile of cytokines, such as IL-2, IL-6, IL-7, INF-γ, and TNF-α, is associated with disease severity and mortality of patients." (PMID 33679608, 2020). "Currently, scientists in the United Kingdom are testing (in a multicenter, Phase 2 clinical trial) the ability of IL-7 to produce an immune reconstitution of COVID-19′s severe patients and observing possible association with their clinical improvement." (PMID 32764275, 2020).
COVID-19 (continued). "Symptoms of severe COVID-19 have been associated with a cytokine storm with high levels of IL-17, IL-10, IL-1β, IL-2, IL-7, IL-8, IL-9, among many other pro-inflammatory cytokines." (PMID 33071815, 2020). "IL-7 was associated with lymphocytes returning to a reference level, appearing to reverse a pathologic hallmark of COVID-19." (PMID 32697322, 2020). "In COVID-19, patient CT lung scan with multiple bilateral lobular pneumonia is associated with IL-1β, IL-7, IL-8, IL-9 level increase in initial plasma concentration." (PMID 32961074, 2020). "Importantly, investigators have demonstrated that ex vivo treatment of blood samples with IL-7 from patients with COVID-19 caused restoration in T cell proliferation and IFN-γ production." (PMID 39903535, 2025). "A dysregulation in cytokine content has been linked to T cell exhaustion in patients who recovered from COVID-19 (n = 39), with higher levels of IL-1β, IL-1RA, IL-7, IL-8, IL-10, IFN-γ, and MIP-1α, and a decrease in IL-9, CCL11, MIP-1β, and RANTES, as compared with healthy controls (n = 43)." (PMID 38549752, 2024). "To explore the mechanisms of decreased expression of PD-1 in CD4+ and CD8+ T cells from convalescent COVID-19 patients, we measured plasma cytokines associated with PD-1 expression, including IL-2, IL-6, IL-7, IL-10, IL-12p70, IL-33, IFN-γ and CCL19/MIP-3, by Luminex." (PMID 38424104, 2024). "Furthermore, an increase in Th17 signalling has been seen in COVID-19 patients with severe infection where increased serum IL-7 signalling was associated with increased T cell depletion." (PMID 38921807, 2024). "Furthermore, COVID-19 caused excessive production of proinflammatory cytokines such as IL-6, IL-2, IL-7, granulocyte-colony stimulating factor (G-CSF), Macrophage Inflammatory Protein-1 Alpha ((MIP-1-α)/CCL3, and TNF-α), termed as cytokine storm." (PMID 37377785, 2023). "Another intriguing observation was the association between LPO with IL-7 and IL-17A levels, which may indicate a mechanism by which COVID-19 leads to a cytokine storm and lymphopenia." (PMID 36499671, 2022). "Thus, elevated levels of SIL-2R and IL-7 are associated with the severity of COVID-19 in patients and with their outcomes." (PMID 36142255, 2022). "Increased levels of IL-7 have been observed in patients with severe COVID-19, the cause of which is unknown." (PMID 35562935, 2022). "Thus, we summarize here the pathogenic and therapeutic role of IL-7 in COVID-19 patients and highlight the promising role of IL-7 as vaccine adjuvant." (PMID 34603318, 2021). "Impaired circulating innate lymphoid cells (ILCs) were reported in severe COVID-19 patients, and these could also be associated with defects in IL-7/IL-7R signaling." (PMID 34603318, 2021). "Overall, CEC attributes of convalescent COVID-19 patients correlated with a vast majority of differentiation and activation factors associated with T cells and B cells (IL-4, IL-5, IL-7, IL-17A, IL-18, MIP-1α, and RANTES), implicating a broad adaptive immune response with endothelial dysfunction." (PMID 33752798, 2021). "This may be due to increased expression of cytokines, including interleukin (IL)-2, IL-6, IL-7, tumor necrosis factor, granulocyte colony-stimulating factor, interferon-gamma, and free radicals associated with the severity of COVID-19." (PMID 32953353, 2020). "This case series examines whether interleukin 7 (IL-7) is associated with restored host protective immunity in patients with severe coronavirus disease 2019 (COVID-19) and immunosuppression." (PMID 32697322, 2020). "Therefore, lower plasma levels of IL-7 in COVID-19 patients imply another possible mechanism underlying lymphopenia in COVID-19 disease, which could be overcome by the therapeutic benefits of IL-7 therapy." (PMID 35284964, 2022).
COVID-19 (continued). "Since we showed that IL-7 treatment augmented perforin levels without significantly increasing TNF-α and IFN-γ production, this may indicate that IL-7 therapy might enhance the functionality of MAIT cells without contributing to the cytokine storm associated with severe COVID-19." (PMID 34238985, 2021). "The study aimed to assess the blood IL-2 and IL-7 concentration in relation to the obtained cellular and humoral response in adults six months after vaccination against COVID-19." (PMID 41305439, 2025). "Given this knowledge, IL-7 can serve as a biomarker for COVID-19 severity and a potential therapeutic tool." (PMID 39940645, 2025). "These cellular changes were accompanied by a sustained increase in serum IL-7 and IL-15 levels in patients after severe COVID-19 up to 6 months after acute infection." (PMID 41310351, 2025). "Further study on the contribution of IL-2 and IL-7 to immune response effects of vaccination against COVID-19 is needed." (PMID 41305439, 2025). "We conducted a prospective, double-blind, randomized, placebo-controlled trial of CYT107, recombinant human IL-7, in 109 critically ill, patients with lymphopenia who have COVID-19." (PMID 39903535, 2025). "IL-7 has been studied as a potential therapeutic for treating patients with severe COVID-19 with lymphopenia and lymphocyte exhaustion." (PMID 40650217, 2025). "Despite the fact that the subject of research is IL-2 and IL-7 concentrations, there are few publications dealing with the post-vaccination response against COVID-19." (PMID 41305439, 2025). "It is possible that increased IL-7 concentration promotes the effectiveness of the COVID-19 vaccination response despite having a history of chronic disease." (PMID 41305439, 2025). "The study aims to assess the blood IL-2 and IL-7 concentration in relation to the obtained cellular and humoral response in adults, six months after vaccination against COVID-19." (PMID 41305439, 2025). "This classifier reinforced the prognostic importance of monocyte/macrophage, NK cell, and Th1-pathway activation, with prediction of severe COVID-19 driven by higher concentrations of IL-7, CXCL10, IL-15, and CXCL9, and lower concentrations of MDC and IL-5." (PMID 38368384, 2024). "For many of the most important mediators identified in predictive models of COVID-19 severity, concentrations appeared divergent early and throughout the course of symptoms, including IL-7, IL-10, lymphotoxin-α, TGF-α, VEGF-A, and MDC." (PMID 38368384, 2024). "Using the REAC pathway analysis of differentially expressed genes in COVID-19-positive cases, we detected interleukin IL-2, IL-7, and IL-10 as well as IL-1, IL-4, IL-13, and IL-36." (PMID 38240884, 2024). "In an individual concerned with COVID-19, it is diagnosed as the increase of IL-2 IL-7, along with other interleukins and chemokines." (PMID 37742314, 2024). "The levels of IL-7 in patients diagnosed with COVID-19 have been shown to be elevated, prompting current investigations on their association with the severity of the illness." (PMID 37742314, 2024). "In the case of IL7, its elevation was shown to correlate with COVID-19 severity directly, with exhaustion of T cells being a possible mediator." (PMID 38455043, 2024). "Individuals affected by COVID-19 who need treatment in intensive care units usually have high levels of interleukin (IL)-2, IL-7, IL-10, tumor necrosis factor α (TNF-α), and other pro-inflammatory and also anti-inflammatory cytokines." (PMID 37408184, 2023). "In this study we found persistent elevation of multiple mediators – IL-6, TNFα, SAA, Tie-2, Flt1, PIGF, and CRP – and persistent depression of IL-7 and bFGF in patients recovering from COVID-19 several months following their acute infection." (PMID 36844209, 2023). "So, in immunosuppressed COVID-19 patients, immunotherapy with IL-7 can restore immunity and result in better clinical outcomes." (PMID 37649897, 2023).
COVID-19 (continued). "Following treatment with Allocetra–OTS, most of these inflammatory immune-modulators, including IL-6, IFN-γ, IL-10, TNFR1, IP-10, MCP-3, and IL-7, gradually decreased to normal levels with resolution of COVID-19." (PMID 37600829, 2023). "The highly expressed cytokines in COVID-19 patients included IL-10, IL-6, IL-7, TNF-α, IFN-α, CCL2, and CCL4, but only incubation monocytes with IL-10 downregulated HLA-DR expression." (PMID 36834656, 2023). "Expression levels of IL-6, TNF-α, IFN-γ, IL-10, IL-12p70, IL-1β, IL-8, IL-13, IL-2, IL-7, IL-17A, IL-5 and IL-7 were measured in saliva and serum pairs obtained from the COVID-19 patients with available baseline symptoms information." (PMID 36846089, 2023). "In patients admitted to medical emergencies with a confirmed diagnosis of COVID-19, it is important to perform a joint evaluation of demographic characteristics, clinical parameters, interleukins (IL-2, IL-6, IL-7, IL-10, IL-17) and sP-selectin." (PMID 36835858, 2023). "Strikingly, other type 1 cytokines, such as IL-12, IFNγ and IL-7, were significantly lower in long-term carriers compared with regular COVID-19 patients at disease onset (<7 DSSO)." (PMID 37529320, 2023). "Patients with severe COVID-19 showed significant increases in cytokines, including IL-2, IL-7, IL-10, GSCF, IP10, MCP-1, MIP1A and TNF-α, with the characteristics of a cytokine storm." (PMID 37112613, 2023). "IL-7 immunotherapy is currently being evaluated as a treatment to reverse the lymphopenia in COVID-19 patients, with good results for critically ill COVID-19 patients." (PMID 35159352, 2022). "Severe COVID-19 is known to cause a cytokine storm, in which over-activated lymphocytes secrete many cytokines such as interleukins (ILs); (IL2, IL6, IL7, etc.), and tumor necrosis factor (TNF)." (PMID 35615724, 2022). "IL-7 administration can be safe for those with life-threatening COVID-19, and can restore the lymphocytes to a usual number, appearing to reverse a pathologic characteristic of COVID-19." (PMID 35782361, 2022). "The evidence also indicated that the severity of COVID-19 increases with the levels of inflammatory mediators including cytokines and chemokines such as IL-2, IL-7, IL-10, and TNF-α in the blood due to COVID-19 infection." (PMID 36091037, 2022). "The COVID-19 group had significantly higher plasma levels of IL-1β, IL-4, IL-7, IL-8, IL-12, TNF, IP-10, eotaxin, GM-CSF, bFGF, complement TCC and C3bc, and significantly lower levels of IL-13 and MIP-1α, as compared to controls." (PMID 35222429, 2022). "Inhibits JAK3, JAK1, JAK2, and to a lesser extent TYK2 and inhibits receptor signaling through pairs of JAK2 and because it can suppress the production of different cytokines, such as IL-2, IL-7 and IL-6 can used for patients with COVID-19." (PMID 36111104, 2022). "We have developed an innovative strategy to deliver in a broad range of organs the IL-7 cytokine with the goal to restore both innate and adaptive immunity of immunosuppressed patients with bacterial sepsis and COVID-19." (PMID 36045686, 2022). "The results show that TGF-β, CXCL-10, IFN gamma, and IL-7 affect mortality in COVID-19 patients in a univariate regression analysis." (PMID 36286038, 2022). "Veillonella, an opportunistic pathogen enriched in COVID-19, was found to lead to Th17 cell recruitment, neutrophil enrichment, and IL7 inflammatory phenotype activation." (PMID 36033885, 2022). "The involvement of the immune system is evident in COVID-19 patients; significant increment of chemokines and cytokines including IL7, IL8, IL9, IL10, IL1-β, IL1RA, GM-CSF, MCP1, MIP1α, and MIP1β is observed." (PMID 36369012, 2022). "Our findings also align with the results of a study conducted on 41 COVID-19 confirmed cases in China, which found that IL-6, IL-7, TNF, and IL-10 were upregulated in the plasma of the study subjects." (PMID 36239108, 2022).